BCAR3 (BCAR3 adaptor protein, NSP family member)
Description:
Acts as an adapter protein downstream of several growth factor receptors to promote cell proliferation, migration, and redistribution of actin fibers. Specifically involved in INS/insulin signaling pathway by mediating MAPK1/ERK2-MAPK3/ERK1 activation and DNA synthesis. Promotes insulin-mediated membrane ruffling (By similarity). In response to vasoconstrictor peptide EDN1, involved in the activation of RAP1 downstream of PTK2B via interaction with phosphorylated BCAR1. Inhibits cell migration and invasion via regulation of TGFB-mediated matrix digestion, actin filament rearrangement, and inhibition of invadopodia activity (By similarity). May inhibit TGFB-SMAD signaling, via facilitating BCAR1 and SMAD2 and/or SMAD3 interaction (By similarity). Regulates EGF-induced DNA synthesis. Required for the maintenance of ocular lens morphology and structural integrity, potentially via regulation of focal adhesion complex signaling (By similarity). Acts upstream of PTPRA to regulate the localization of BCAR1 and PTPRA to focal adhesions, via regulation of SRC-mediated phosphorylation of PTPRA (By similarity). Positively regulates integrin-induced tyrosine phosphorylation of BCAR1 (By similarity). Acts as a guanine nucleotide exchange factor (GEF) for small GTPases RALA, RAP1A and RRAS (By similarity). However, in a contrasting study, lacks GEF activity towards RAP1.
Synonyms: NSP2; SH2D3B; AND-34; MIG7
Tractability: Small molecule: a structure with a bound ligand is known. Antibody: the Human Protein Atlas places it where antibodies can reach. PROTAC: ubiquitination databases record sites on it.
Gene: Protein-coding gene on chromosome 1 (93,561,741 to 93,847,488, reverse strand). Ensembl gene ENSG00000137936.
Subcellular location: Cytoplasm; Cell junction, focal adhesion
Subcellular location (Human Protein Atlas): Cytosol; Plasma membrane; Centrosome
Gene Ontology:
Molecular function: kinase binding; phosphotyrosine residue binding; protein binding; guanyl-nucleotide exchange factor activity
Biological process: endothelin receptor signaling pathway; epidermal growth factor receptor signaling pathway; insulin receptor signaling pathway; positive regulation of cell population proliferation; positive regulation of GTPase activity; positive regulation of MAPK cascade; response to xenobiotic stimulus; signal transduction; small GTPase-mediated signal transduction
Cellular component: cytoplasm; focal adhesion; membrane
Genetic constraint (gnomAD): Loss-of-function variants: 37 observed, 83.31 expected, observed/expected ratio (o/e) 0.44, 90% interval 0.34 to 0.58. The upper end of that interval is the gene's LOEUF score, 0.58, which puts it in group 2 of 6, group 1 being the genes least tolerant of losing a copy. Missense variants: 978 observed, 1,103.2 expected, observed/expected ratio (o/e) 0.89, 90% interval 0.84 to 0.94. Synonymous variants: 389 observed, 435.38 expected, observed/expected ratio (o/e) 0.89, 90% interval 0.82 to 0.97.
Homologues: Orthologues: chimpanzee BCAR3 (99% identical), macaque BCAR3 (96% identical), guinea pig BCAR3 (87% identical), dog BCAR3 (86% identical), rat Bcar3 (86% identical), mouse Bcar3 (85% identical), rabbit BCAR3 (85% identical), pig BCAR3 (85% identical), tropical clawed frog bcar3 (64% identical), zebrafish bcar3 (58% identical), Drosophila melanogaster CG9098 (30% identical). Paralogues in human: SH2D3C (39% identical), SH2D3A (27% identical).
Diseases named in the same sentence as BCAR3 in open-access papers:
BCAR3 is named in the same sentence as 30 diseases in open-access papers, as found by Europe PMC text mining. Sharing a sentence is not in itself a finding about the gene and the disease. The quoted sentences say what the papers report.
breast carcinoma (40 papers, 2005 to 2025). "BCAR3 has already been associated with breast cancer pathogenesis, however the specific mechanisms regulating BCAR3 functions remained elusive." (PMID 38296970, 2024). "The ISR2 protein is overexpressed in many cancer types and in vivo has been shown to enhance metastasis, BCAR3 is associated cellular migration and resistance to therapeutic anti-estrogens in breast cancer cells." (PMID 33859638, 2021). "On the clinical level, BCAR3 was found to be associated with the survival and prognosis of patients with breast cancer." (PMID 34707118, 2021). "Hsa_circRNA_007624 was the most downregulated circRNA and transcribed from the BCAR3 gene, which encodes proteins to induce the resistance to antiestrogens of breast cancer cells." (PMID 33747034, 2021). "BCAR3 is a protein-coding gene, diseases associated with BCAR3 include estrogen resistance, breast cancer, and cataracts." (PMID 30563570, 2018). "Breast Cancer Antiestrogen Resistance 3 (BCAR3) is a protein-coding gene that is associated with many tumors." (PMID 30563570, 2018). "BCAR3 was especially interesting as a potential target of tRF5-Glu because it has been extensively studied in breast cancer as a protein associated with anti-estrogen resistance." (PMID 29221134, 2017). "The expression of BCAR3 in breast cancer cells has been previously associated with increased proliferation." (PMID 29221134, 2017). "Taken together, our study indicates that BCAR3 is a novel antagonist of TGFβ proinvasive functions in breast cancer cells, and loss of BCAR3 function correlates with poor outcomes in breast cancer patients." (PMID 25499443, 2014). "We also found a strong correlation between the loss of heterozygosity at BCAR3 gene alleles and lymph node invasion in human breast cancer, further suggesting a role for BCAR3 in preventing disease progression." (PMID 25499443, 2014). "Given that the establishment of membrane protrusions is a critical facet of cell migration and the loss of BCAR3 has been shown to decrease breast cancer cell motility, we sought to determine the contribution of BCAR3 to membrane protrusiveness." (PMID 23762409, 2013). "AND-34/BCAR3 (Breast Cancer Anti-Estrogen Resistance 3) associates with the focal adhesion adaptor protein, p130CAS/BCAR1." (PMID 19365570, 2009). "BCAR3 and p130Cas were associated with anti-estrogen in breast cancer, Rac activation." (PMID 30563570, 2018). "Another gene is BCAR3, which is associated with estrogen resistance and breast cancer." (PMID 29671401, 2018). "Furthermore, STF noticeably induced several gene expressions associated with breast cancer anti-estrogen resistance 3 (BCAR3), cluster of differentiation 83 (CD83), nucleotide-binding oligomerization domain containing 2 (NOD2)." (PMID 28068976, 2017). "BCAR3 is considered to be associated with aggressive breast cancer phenotypes." (PMID 25499443, 2014). "This not only demonstrates a true prognostic value for BCAR3 but also implicates that loss of BCAR3 expression may be involved in breast cancer progression." (PMID 25499443, 2014). "tRF5-Glu binds directly to a site in the 3′UTR of the breast cancer anti-estrogen resistance 3 (BCAR3) mRNA, downregulating its expression and inhibiting ovarian cancer cell proliferation." (PMID 40295511, 2025). "BCAR3’s role in anti-estrogen resistance particularly highlights its potential as a therapeutic target in hormone-responsive cancers, such as breast cancer." (PMID 38730626, 2024). "The interplay between BCAR3 and cancer stem cells (CSCs) remains an underexplored terrain, particularly in the domain of breast cancer where CSCs exhibit unique characteristics." (PMID 38730626, 2024). "Corresponding with elevated BCAR3 and SMYD2 levels, we detected a robust endogenous BCAR3 methylation signal using the specific BCAR3 K334me1 antibody in the metastatic breast cancer lines." (PMID 38296970, 2024).
breast carcinoma (continued). "The BCAR3 gene, identified in 1998, has emerged as a significant factor in the context of estrogen-independent growth in breast cancer." (PMID 38730626, 2024). "This article provides an in-depth review of the Breast Cancer Anti-Estrogen Resistance 3 (BCAR3) gene, focusing on its significant implications in cancer progression." (PMID 38730626, 2024). "We further validated SMYD2 as the principal enzyme tasked with generating physiologic BCAR3 K334me1, based on both depletion and reconstitution experiments in multiple independent breast cancer cell lines." (PMID 38296970, 2024). "Utilizing genetically modified mice that express a chimeric MHC molecule amalgamating human and murine components, the study examines phosphorylated BCAR3 expression in human-derived melanoma and breast cancer cell lines through Western blot analysis." (PMID 38730626, 2024). "This research promises not only to fill a significant void in our understanding of BCAR3’s role in breast cancer but also sets the stage for the development of novel CSC-targeted therapies." (PMID 38730626, 2024). "BCAR3’s overexpression in breast cancer cells notably boosts ERK1/2 activation through c-SRC, with phosphorylation markers indicating enhanced activity." (PMID 38730626, 2024). "Furthermore, if BCAR3 is implicated in the maintenance of CSCs, it could emerge as a promising target for therapies aimed at eradicating this challenging cell population, potentially leading to more durable responses in breast cancer treatment." (PMID 38730626, 2024). "Mechanistically, we identify BCAR3 as a genuine physiological substrate of SMYD2 in breast cancer cells." (PMID 38296970, 2024). "In conclusion, the BCAR1 and BCAR3 interaction triggers a comprehensive signaling cascade that culminates in anti-estrogen resistance in breast cancer cells." (PMID 38730626, 2024). "Breast cancer cells with impaired BCAR3 methylation lose migration and invasiveness capacity in vitro and are ineffective in promoting metastases in vivo." (PMID 38296970, 2024). "The CRK adaptors are also linked to breast cancer anti-estrogen resistance proteins BCAR1 and BCAR3, which also associate with each other." (PMID 37686522, 2023). "Elevated expression of BCAR3 has been shown to increase the proliferation, motility, and invasiveness of estrogen receptor-positive breast cancer cells after treatment with antiestrogens." (PMID 36961501, 2023). "This chromosomal region is a breast cancer anti-estrogen resistance 3 (BCAR3) mRNA transcript composed of 20 exons." (PMID 35962012, 2022). "It has been shown that there is a relationship between BCAR3 expression and the regulation of breast cancer cell migration through a change in the location of BCAR1 in the cytoplasmic membrane." (PMID 35453754, 2022). "Recent studies have shown that BCAR3 leads to the inhibition of breast cancer progression through blockage of the TGFß/Smad signaling pathway." (PMID 35453754, 2022). "For example, 5′ tRF-Glu bound to the 3′ UTR of breast cancer anti-estrogen resistance 3 (BCAR3) mRNA and decreased the expression level of BCAR3 which can suppress proliferation in ovarian cancer development." (PMID 36072340, 2022). "An increase in BCAR3 activity has been observed in advanced breast cancer cells, indicating a relationship between intracellular signal transduction through BCAR3 and the intensity of metastasis." (PMID 35453754, 2022). "Like Cas, BCAR3 protects estrogen-dependent breast cancer cells from inhibitory actions of anti-estrogens." (PMID 34169835, 2021). "The majority of studies at the cell level found that BCAR3 promotes breast cancer progression through the development of estrogen resistance, promotion of CCND1 expression, promotion of migration and invasion, and regulation of adhesion signaling." (PMID 34707118, 2021). "Over-expression of BCAR3 in fibroblasts and breast cancer cells stimulates Cas-dependent functions, such as lamellipodia ruffling." (PMID 34169835, 2021).
breast carcinoma (continued). "Breast cancer anti-estrogen resistance protein 3 (BCAR3) is involved in anti-estrogen resistance and other important aspects of breast cancer." (PMID 34707118, 2021). "The analysis of our RNAseq data also showed an upregulation of the BCAR3 gene, engaged in enhanced cancer cell motility, by regulation of the balance between Rac1 and RhoA signaling in invasive breast cancer cells." (PMID 35008571, 2021). "It is worth noting that existing studies on BCAR3 have mainly focused on its molecular mechanism and clinical significance in breast cancer." (PMID 34707118, 2021). "Lebrun and colleagues indicated that BCAR3 acts as a putative suppressor of breast cancer progression by inhibiting the prometastatic transforming growth TGFβ/Smad signaling pathway, which helps explain the differences among studies." (PMID 34707118, 2021). "Of the two consistent genes, Bcar3 is involved in cell proliferation, which when overexpressed in breast cancer conveys estrogen resistance, and Tmem242 is a transmembrane protein with very little current annotation." (PMID 29549885, 2018). "So, overexpression of BCAR3 in breast cancer cells can promote cell migration and invasion in most researches." (PMID 30563570, 2018). "BCAR3 has been well studied in breast cancer for its role in anti-estrogen resistance and breast cancer cell proliferation." (PMID 29221134, 2017). "We confirmed that tRF5-Glu binds directly to a site in the 3’UTR of the Breast Cancer Anti-Estrogen Resistance 3 (BCAR3) mRNA thereby down regulating its expression." (PMID 29221134, 2017). "Ectopic overexpression of BCAR3 in breast cancer cells activates Src and FAK kinases, leading to p130Cas tyrosine phosphorylation and increased cell attachment to fibronectin and cell motility." (PMID 25499443, 2014). "In fact, the results of a previous study and our present results both demonstrate that knocking down BCAR3 in basal-like breast cancer cells impairs cell migration." (PMID 25499443, 2014). "We initially examined the relative protein expression levels of BCAR3 and p130Cas in a panel of breast cancer cell lines representing different molecular subtypes and phenotypes of breast tumors." (PMID 25499443, 2014). "Our results also highlight potential prognostic value of BCAR3 in human breast cancer, as we found low BCAR3 expression levels in primary breast tumors to be correlated with poor outcomes, regardless of treatment plans." (PMID 25499443, 2014). "We surveyed functional genomics databases for correlations between BCAR3 expression and disease outcomes of breast cancer patients." (PMID 25499443, 2014). "We found that, similarly to previously reported findings, BCAR3 expression levels were relatively high in estrogen-independent breast cancer cells." (PMID 25499443, 2014). "For this purpose, we stimulated a panel of basal-like breast cancer cell lines with TGFβ for 24 hours and examined the protein levels of BCAR3." (PMID 25499443, 2014). "Our study provides new insights into BCAR3’s mechanism of action and suggests a need to reevaluate the implications of BCAR3’s role in breast cancer pathology." (PMID 25499443, 2014). "This study helps to define the implications of breast cancer anti-estrogen resistance 3 (BCAR3) in breast cancer and extends the current understanding of its molecular mechanism of action." (PMID 25499443, 2014). "It is important to mention that BCAR3’s roles in aggressive behavior of breast cancer cells are twofold." (PMID 25499443, 2014). "Taken together, these results suggest a positive feedback loop mechanism by which TGFβ/Smad signaling represses expression of its own inhibitory molecule, BCAR3, further leading to enhanced TGFβ/Smad signaling in breast cancer cells." (PMID 25499443, 2014). "We also found BCAR3 protein levels in breast cancer cells to be controlled by TGFβ, as TGFβ treatment decreases BCAR3 expression in a Smad-dependent and proteasome-dependent manner." (PMID 25499443, 2014).
breast carcinoma (continued). "Taken together, our results demonstrate that BCAR3 antagonizes TGFβ-induced Smad activation in several breast cancer cell lines." (PMID 25499443, 2014). "The results of our clinical data survey and analysis define BCAR3 as a single factor whose expression level is predictive of clinical outcomes in breast cancer patients." (PMID 25499443, 2014). "The data presented above showing that BCAR3 regulates the cytoskeletal response of invasive breast cancer cells to EGF thus provide a second point of convergence between BCAR3 and intracellular signaling pathways that control tumor cell motility and invasion." (PMID 23762409, 2013). "We show that BCAR3 is a positive regulator of Rac1 activity, membrane protrusiveness, and adhesion turnover in invasive breast cancer cells." (PMID 23762409, 2013). "Taken together, these data indicate that adhesion dynamics, particularly disassembly, are regulated by BCAR3 in invasive breast cancer cells." (PMID 23762409, 2013). "In this study, we set out to determine the mechanism through which BCAR3 promotes breast cancer cell motility by examining its function in the regulation of membrane protrusions, adhesion turnover, and contractility." (PMID 23762409, 2013). "In this work, we focus on the adaptor molecule Breast Cancer Antiestrogen Resistance 3 (BCAR3), which has emerged as an important regulator of breast cancer cell migration and invasion." (PMID 23762409, 2013). "In the current study, we show that BCAR3 is necessary for membrane protrusiveness, Rac1 activity, and adhesion disassembly in invasive breast cancer cells." (PMID 23762409, 2013). "Taken together, these data establish that BCAR3 functions as a positive regulator of cytoskeletal remodeling and adhesion turnover in invasive breast cancer cells through its ability to influence the balance between Rac1 and RhoA signaling." (PMID 23762409, 2013). "Like BCAR3, these molecules are established regulators of cell motility, antiestrogen resistance, and other aggressive breast cancer behaviors." (PMID 23762409, 2013). "BT549 cells, which are invasive breast cancer cells that express high levels of BCAR3, were transfected with control (siCtl) or BCAR3-specific (siB3-1) siRNA oligonucleotides and imaged by time-lapse video microscopy." (PMID 23762409, 2013). "Based on these data, we suggest that BCAR3 controls the balance between Rac1 and RhoA signaling in invasive breast cancer cells and, through this activity, functions as a positive regulator of actin cytoskeletal/adhesion remodeling and cell motility." (PMID 23762409, 2013). "In this work, we show that BCAR3, an adaptor molecule that regulates cell motility and invasion, tips the balance in favor of Rac1 in invasive breast cancer cells, thus promoting Rac1-dependent events such as membrane protrusions and adhesion turnover." (PMID 23762409, 2013). "Previous work from our group showed that elevated BCAR3 protein levels enhance cell migration, while depletion of BCAR3 reduces the migratory and invasive capacities of breast cancer cells." (PMID 23762409, 2013). "Our group has shown that elevated BCAR3 protein expression in breast cancer cells promotes c-Src/Cas interactions, c-Src kinase activity, c-Src-dependent Cas tyrosine phosphorylation, Cas/CrkII association, and Rac1 activity (and data herein)." (PMID 23762409, 2013). "There is considerable evidence for a role of EGF in promoting breast cancer cell invasion, and we have shown that BCAR3 can regulate the migration/invasion of breast tumor cells toward EGF." (PMID 23762409, 2013). "Among the three NSP family members, only AND-34/BCAR3 induces anti-estrogen resistance in estrogen receptor (ERα)-positive breast cancer cell lines." (PMID 19365570, 2009). "Conversely, depletion of AND-34/BCAR3 in mesenchymal breast cancer cells by RNA interference inhibits cell migration and invasiveness and relocalizes p130CAS away from the membrane." (PMID 19365570, 2009).